TTK (TTK protein kinase)
Diseases named in the same sentence as TTK in open-access papers (continued):
Sharing a sentence is not in itself a finding about the gene and the disease.
Cirrhosis (1 paper, 2022). A chronic disorder of the liver in which liver tissue becomes scarred and is partially replaced by regenerative nodules and fibrotic tissue resulting in loss of liver function. "It is concluded that BUB1B, NUSAP1, TTK, HMMR, CCNA2, and KIF2C can be considered as potential novel molecular indicators for the onset and development of HCC, since they are linked to the transition from cirrhosis to HCC." (PMID 36199789, 2022).
colon adenocarcinoma (1 paper, 2023). "Elevated expression of TPX2 and TTK correlated with an oncogenic state in tumor tissue from patients with colon adenocarcinoma, thus corroborating an oncogenic role for the TPX2/TTK network in the pathogenesis of CRC." (PMID 37770979, 2023).
colorectal tumor (1 paper, 2025). "Also, these results were experimentally confirmed in gastric and colorectal tumor tissues, and ROC curve analysis emphasized the potential of TTK mRNA expression as a diagnostic biomarker to distinguish cancerous tissue from normal tissue." (PMID 40723362, 2025).
COVID-19 (1 paper, 2022). A disease caused by infection with severe acute respiratory syndrome coronavirus 2. "The network pharmacology analysis identified seven core targets (namely, AURKA, CDK1, CCNB1, CCNB2, CCNE1, CCNE2, and TTK) of curcumol in patients with COVID-19 and LUAD." (PMID 35520289, 2022). "The molecular network analysis using Cytoscape highlighted seven core targets of curcumol, namely, AURKA, CDK1, CCNB1, CCNB2, CCNE1, CCNE2, and TTK in COVID-19 and LUAD." (PMID 35520289, 2022). "We identified seven core pharmacological targets of curcumol, namely, AURKA, CDK1, CCNB1, CCNB2, CCNE1, CCNE2, and TTK, in treating LUAD and COVID-19." (PMID 35520289, 2022). "The targeting of CDK1 and TTK by curcomol provides an opportunity to treat patients with LUAD and COVID-19." (PMID 35520289, 2022).
gastric tumor (1 paper, 2025). "The violin plot showed that the expression levels of the AURKA, CEP55, DTL, and TTK genes were significantly increased in colorectal and gastric tumor tissues (p value < 0.05)." (PMID 40723362, 2025).
gynecological cancers (1 paper, 2024). "Notably, TTK is highly expressed in gynecological cancers, including CESC, OV, UCEC and UCS." (PMID 38195567, 2024).
Lewis lung carcinoma (1 paper, 2016). "Furthermore, inhibition of RSK and TTK reduced tumor growth, vascular density, and improved survival in an in vivo Lewis lung carcinoma mouse model." (PMID 27618721, 2016).
lymph node metastasis (1 paper, 2022). "High TTK expression was found to be associated with later histological stage, higher TNM stage, lymph node metastasis, and poorer 5-year overall survival." (PMID 35784389, 2022). "In addition, the incidence of lymph node metastasis in the high TTK expression group was significantly higher than that in the low TTK expression group." (PMID 35784389, 2022).
medulloblastoma (1 paper, 2023). A malignant, invasive embryonal neoplasm arising from the cerebellum. "Another small-molecule inhibitor, NMS-P715 has previously been shown to inhibit TTK expression in medulloblastoma, resulting in suppression of cell growth and clonogenic potential, as well as induction of apoptosis, further reaffirming our findings from the current study." (PMID 37770979, 2023).
meningioma (1 paper, 2023). A generally slow growing tumor attached to the dura mater. "Furthermore, of the four DREAM complex target genes shown to be upregulated in type C tumors, only PBK was higher in our NF2-2 meningiomas, while the expression of the 3 other genes (TTK, MELK, and CDK1) was not significantly different between the subgroups." (PMID 36937440, 2023).
metastatic prostate carcinoma (1 paper, 2022). A carcinoma that arises from the prostate gland and has spread to other anatomic sites. "It demonstrates a tightly associated sub-network of the meiotic cell cycle with strictly meiosis-specific (i.e., HORMAD1, MND1, SMC1B) genes and includes CT genes such as TTK and PBK (known also for metastatic prostate carcinoma)." (PMID 36499258, 2022).
osteoarthritis (1 paper, 2014). A noninflammatory degenerative joint disease occurring chiefly in older persons, characterized by degeneration of the articular cartilage, hypertrophy of bone at the margins and changes in the synovial membrane. "Proteins such as CD5 molecule-like protein (CD5L), soluble scavenger receptor cysteine-rich domain-containing protein (SSC5D), and TTK protein kinase (TTK) were found to be upregulated in the synovial fluid of osteoarthritis patients." (PMID 24393543, 2014).
ovarian tumor (1 paper, 2021). "We verified that the protein expression of TTK in ovarian tumor tissues was indeed higher than in normal controls by way of microarray chips- (P < 0.01)." (PMID 34598710, 2021).
prostate tumors (1 paper, 2012). "The fact that 18% of human prostate tumors overexpress TTK and that these tumors have a different clinical outcome suggests that TTK inhibitors in combination with antiandrogens may be of interest." (PMID 22509301, 2012). "The large number of prostate tumors with alterations in STRADA, TTK, and AKT1 expression led us to look at their correlation with biochemical recurrence." (PMID 22509301, 2012). "Of the 218 prostate tumors, 34.4% had reduced expression of STRADA, 18.3% exhibited overexpression of TTK, 11.7% either overexpressed or had reduced expression of AKT1, and 15.6% of tumors overexpressed or had amplified AR." (PMID 22509301, 2012). "Unlike AR, STRADA, TTK, and AKT1 showed little evidence of gene amplification or loss in human prostate tumors." (PMID 22509301, 2012).
renal carcinoma (1 paper, 2023). A carcinoma arising from the epithelium of the renal parenchyma or the renal pelvis. "Compared with the renal cancer patients with low expression of TTK, the patients with high expression of TTK have the poor overall survival (P = 0.0021)." (PMID 36849137, 2023). "Gene Expression Profiling Interactive Analysis (GEPIA) was performed to explore the role of TTK on the overall survival of renal cancer." (PMID 36849137, 2023). "There is a positive correlation between expression of TTK and the pathological stage of renal cancer (P < 0.05)." (PMID 36849137, 2023). "And TTK was also one significant hub biomarker of renal cancer." (PMID 36849137, 2023). "Compared with the normal tissues, the expression of TTK in the renal cancer was higher." (PMID 36849137, 2023).
rheumatoid arthritis (1 paper, 2022). A chronic, systemic autoimmune disorder characterized by inflammation in the synovial membranes and articular surfaces. "Based on the Gene Expression Omnibus (GEO) database, GZMA, PRC1 and TTK were enriched in the innate immune cell-mediated immune response and immune-related biological processes, validating them as potential targets for rheumatoid arthritis (RA) therapy." (PMID 35651940, 2022).
serous carcinoma (1 paper, 2023).
uterine cancer (1 paper, 2023). Primary or metastatic malignant neoplasm involving the uterine corpus and/or the cervix. "We also demonstrate the inhibitory effect of BAY1217389, a TTK inhibitor recently tested in a Phase I clinical trial for the treatment of solid tumors, on uterine cancer cell line viability." (PMID 37141409, 2023). "Using DEC-Tec or other drug discovery platform, one might identify novel small-molecule inhibitors of kinase genes in uterine cancer, including TTK and MASTL, representing future work from our previous study." (PMID 37141409, 2023).
uterine tumours (1 paper, 2018). "To further confirm whether PTEN mutated tumours restored HR repair deficiency, we investigated the relationship between PTEN mutation and HR-related genes (HR signature, TTK and DEPDC1) in colon and uterine tumours including non-hypermutators." (PMID 29880869, 2018).
cancer (147 papers, 2010 to 2026). A tumor composed of atypical neoplastic, often pleomorphic cells that invade other tissues. "Several SAC proteins, including budding uninhibited by benzimidazole (BUB), mitotic arrest deficient (MAD), and the serine/threonine kinase TTK protein kinase (TTK), are often overexpressed in cancers." (PMID 40269198, 2025). "It has been shown that genetic or siRNA‐mediated TTK depletion makes cancer cells susceptible to X‐ray induced G2/M arrest in vitro, as the kinase regulates CHK2 sensing improper chromosome alignment during anaphase." (PMID 40165380, 2025). "TTK overexpression is significantly associated with reduced overall survival (OS) in patients with BC, as well as with cancer progression and poor prognosis in the triple‐positive BC (TPBC) subtype." (PMID 39775836, 2025). "Further research is required to identify the molecular mechanisms underlying the interaction between ANXA2 and TTK in other cancers." (PMID 38658569, 2024). "TTK inhibitors like BOS172722 and CFI-402257 have shown promise in cancer treatment, making TTK a potential independent diagnostic biomarker and therapeutic target for specific HCC subtypes." (PMID 38728362, 2024). "The particular suppression of TTK activity by the NMS‐P715 (CID: 44556162) molecule is associated with potential anti‐proliferative action in human cancer cells, as seen in both in vitro and in vivo experiments using mouse xenograft models." (PMID 38717954, 2024). "The filtered blue module (203 genes) contained several genes associated with various typesof cancers and cell cycle regulation, including TTK, PLK1, LRG1, and CDK1." (PMID 39439565, 2024). "The TTK protein is commonly overexpressed in PC, and the loss of the TTK gene inhibited cancer cell proliferation and transformation growth, where TTK was crucial in preventing PC cell death." (PMID 37504265, 2023). "To further discover genomic alterations in the TTK gene across the pan-cancer population, we conducted gene mutation and copy number alteration analyses using the cBioPortal database." (PMID 36829176, 2023). "In cancer cells, increased TTK expression was linked to increased resistance to nelarabine, mithramycin, and actinomycin D, 6-thioguanine." (PMID 36213834, 2022). "TTK has been considered to be dysregulated in various cancer cells because TTK dysregulation causes excess centrosomes resulting in aberrant mitotic spindles." (PMID 32121246, 2020). "Despite its basic biological function and clinical significance, the underlying mechanisms of TTK-mediated cancer progression remain poorly understood." (PMID 32121246, 2020). "TTK was a gene previously identified in a 25-gene signature associated with chromosomal instability and aneuploidy in cancer." (PMID 28380042, 2017). "These correlations suggest an association between TTK levels and cancer behavior (i.e. cell proliferation, tumor aggressiveness)." (PMID 25278993, 2014). "Dysregulation of TTK can lead to chromosomal instability, a hallmark of cancer, which may contribute to tumour progression and metastasis." (PMID 39775836, 2025). "In conclusion, a novel molecular signature panel including the AURKA, CEP55, DTL, and TTK genes could improve early cancer detection and diagnostic accuracy, and it may contribute to the treatment outcomes of PAN-gastrointestinal cancer patients." (PMID 40723362, 2025). "Furthermore, TTK upregulation has been reported in different cancers and is associated with unfavorable prognosis." (PMID 38195567, 2024). "However, dysregulation of TTK can lead to chromosome missegregation, ultimately resulting in aneuploidy, a hallmark of many cancer types." (PMID 38886738, 2024). "Numerous prior research has examined the association between TTK expression and cancer diagnosis." (PMID 36829176, 2023). "TTK is an important mitotic kinase whose loss of function results in chromosomal segregation defects that can lead to aneuploidy and cell death, making it an attractive drug target for cancer." (PMID 36405310, 2022).
cancer (continued). "However, it is likely that some common NMD-resistant mutations such as TTK will also generate targetable mutant proteins in MSI-High cancers." (PMID 21209843, 2010). "CFI-402257 (luvixasertib, 2257) is a small molecule inhibitor of threonine tyrosine kinase (TTK), a promising therapeutic target in genomically unstable cancers due to its critical role in establishing the spindle assembly checkpoint (SAC) during mitosis." (PMID 41898529, 2026). "Although TTK overexpression has been reported in various cancers, its regulatory mechanisms remain poorly understood." (PMID 39716891, 2025). "Recently published studies and our findings provide strong evidence that TTK is a biomarker for predicting outcomes in several cancer types." (PMID 40723362, 2025). "High TTK activity is known as a predictor for unfavorable disease outcomes in different cancers including MM." (PMID 40165380, 2025). "TTK is essential for mitotic checkpoint complex formation, chromosome alignment, cytokinesis, and DNA damage response, acting as an oncogene in cancers such as thyroid, breast, lung, prostate, and liver." (PMID 40269198, 2025). "A number of TTK inhibitors have been developed and are currently in clinical use for different cancer types." (PMID 39775836, 2025). "Several studies have identified TTK and its effects on G2/M as an attractive target in cancer, including in HNSCC." (PMID 39392349, 2024). "In our study, using a pancancer analysis, we observed aberrant TTK mRNA expression in patients with various cancers, consistent with previous reports." (PMID 38195567, 2024). "TTK expression is increased in prostate, thyroid, esophagal, and other cancer tissues and is correlated with postoperative recurrence and poor prognosis." (PMID 39935706, 2024). "Recent studies and our results strongly indicate that TTK is a biomarker of poor prognosis across cancers." (PMID 38195567, 2024). "Compound 15 degrades AURKA with low DC50 value of 2.05 nM, which is 77-fold and 21-fold more selective toward AURKB and TTK and has an EC50 value of 39 nM against cancer MV4-11 cells." (PMID 39539259, 2024). "A number of TTK and PLK1 inhibitors have entered clinical development for the treatment of cancer, with the TTK inhibitors mainly explored in combination with taxanes and more recently with estrogen receptor (ER) antagonists." (PMID 39184047, 2024). "Earlier studies showed that a few TTK inhibitors, such as MPI-0479605, suppressed the growth of cancer xenografts in immune-deficient mice." (PMID 38410481, 2024). "UALCAN database and Timer 2.0 were also used to investigate TTK expression in various cancer and normal tissues." (PMID 38658569, 2024). "Its function in regulating mitosis and its overexpression in many cancers has promoted research on TTK inhibitors as anticancer targets." (PMID 38658569, 2024). "Although WEE1, PLK1, and AURKA kinase inhibitors have been studied in HNSCC and other cancers, small molecule inhibitors targeting other G2/M kinases such as TTK are currently in preclinical or clinical development." (PMID 39392349, 2024). "Dual TTK/PLK1 inhibition represents a novel approach for the treatment of human cancer, including TNBC patients, with a potential for potent anticancer activity and a favorable therapeutic index." (PMID 39184047, 2024). "Overall, the observations we made with the degrader molecules we developed can further aid in the design and development of optimized TTK or AURK degraders for cancer therapy." (PMID 39539259, 2024). "Since CDK1, CHEK1, KIF11, PLK1 and TTK was significantly elevated with cancer progression in LUAD and exhibited excellent binding performance with 6-MDS, they were chosen for further validation." (PMID 38783288, 2024). "Heightened TTK expression has been consistently documented across diverse cancer types, encompassing lung, breast, liver, kidney, colon, and gastric cancer." (PMID 37894942, 2023).
cancer (continued). "In line with this possibility, cell functional experiments have proven that silencing TTK with shRNA significantly attenuated the proliferative and invasive properties and abolished the resistance to the anti-cancer drug TX." (PMID 36829176, 2023). "It was reported earlier that the overexpression of TTK results in the enlargement of the centrosome and chromosomal instability, ultimately leading to the development of different cancers." (PMID 37304238, 2023). "Typically, TTK and other cancer-testis antigens are expressed in testicular and tumor but not in normal." (PMID 36829176, 2023). "Comprehending the multifaceted roles of TTK in cancer is imperative for the development of targeted therapeutic strategies and the enhancement of patient prognosis." (PMID 37894942, 2023). "Elevated levels of TTK allow the survival of aneuploidy cancer cells and its overexpression has been observed in multiple cancers." (PMID 37815894, 2023). "Compared to patients with other cancer types, patients with EC had the greatest prevalence of TTK alterations." (PMID 36829176, 2023). "In recent years, an expanding corpus of research has spotlighted TTK as a promising target for cancer therapy." (PMID 37894942, 2023). "TTK, described as an oncogene that promotes tumor progression, was highly expressed in various cancers, making it a promising therapeutic target." (PMID 38012786, 2023). "In contrast to other cell cycle checkpoints, the SAC is an essential device for survival in all metazoan cells, including cancer cells; and agents against TTK, APC/C or AURKB have been developed." (PMID 37443114, 2023). "Previous studies involving TTK have not only examined its value for cancer diagnosis, but also analyzed its role in determining the prognosis of cancer patients." (PMID 36829176, 2023). "The inhibition of TTK prompts a premature exit of cancer cells from mitosis, culminating in heightened chromosome segregation errors and the genesis of aneuploid cells." (PMID 37894942, 2023). "Cancer stage-wise expression analysis of the hub genes revealed that the expressions of TTK, BUB1B, and NUSAP1 increased while the expression of ZWINT decreased slightly with the stage-wise continued progression of OC." (PMID 37304238, 2023). "The most important TAAs are HER-2/neu, melanoma-associated antigens-A (MAGE-A), TTK protein kinase (TTK), LAGE-1, and the gene encoding New York’s esophageal squamous cell carcinoma 1 (NY-ESO-1), which is used in cancer vaccines." (PMID 36010836, 2022). "We then analyzed a smaller cohort of TNBC patients from Moffitt Cancer Center (N = 129) for the expression of TTK, active (p-TBK1), Ki-67, Vimentin, and E-cadherin in NHB and NHW patients." (PMID 36494865, 2022). "Silencing TTK is also found to inhibit the proliferation and invasion and increase radiosensitivity and chemosensitivity of cancer cells." (PMID 35873497, 2022). "We also compared the relationship between cancer immune infiltrating cells and tumor mutation burden (TMB) in patients with different TTK expression levels via bioinformatics analysis." (PMID 35784389, 2022). "Studies involving RNA interference-mediated knockdown or chemical inhibition of TTK have validated it as a target for cancer therapeutics." (PMID 36405310, 2022). "Due to its major role in mitotic checkpoint and overexpression in different malignancies, TTK is considered a potential anti-cancer drug target." (PMID 36405310, 2022). "Threonine and tyrosine protein kinase (TTK), which is also known as monopolar spindle 1 (Mps1), acts as an oncogenic gene in a variety of cancers." (PMID 35982956, 2022). "In a human cancer mouse model, oral administration of the TTK inhibitor cfi-402257 alone or in combination with an anti-programmed cell death 1 (PD-1) antibody inhibited tumor growth at a well-tolerated dose." (PMID 35784389, 2022).